IL2 (interleukin 2)
Diseases named in the same sentence as IL2 in open-access papers (continued):
Sharing a sentence is not in itself a finding about the gene and the disease.
autoimmune disease (continued). "The results of similar peripheral IL-2 levels in untreated pAIH as well as in age and gender matched no AIH controls without evidence for liver and autoimmune diseases do not imply an IL-2 deficiency in pAIH." (PMID 28700730, 2017). "Since there are no established human autoimmune diseases containing autoantibodies against IL-2, MHC-DR or λ-LC, commercial antibodies, which produced robust signals in LIPS, were employed as positive controls." (PMID 26599070, 2015). "Autoimmune diseases and a variety of lymphoid neoplasms are also investigated for the therapeutic application of an anti-CD25 antibody as the list of diseases under consideration for a therapeutic modulation of IL-2 signaling is expanding." (PMID 26529512, 2015). "C27 inhibitor showed encouraging success at the preclinical level to effectively inhibit IL-2 production in a mouse model of staphylococcal enterotoxin B-induced IL-2 release (SEB IL-2 model), which makes it a potent and specific PKC-θ inhibitor candidate for therapy in autoimmune diseases." (PMID 26528291, 2015). "Cytokine IL-2 and its interacting partners are indispensable to activation, development and maintenance of T regulatory cells, and disruption of IL2-mediated pathways promotes progression of autoimmune disorders." (PMID 24098138, 2013). "IL2 and IL21 genes are both functional candidates for autoimmune diseases as they may be involved in the regulation of T-cells responses." (PMID 22876110, 2012). "IL-2 mediates the cooperation of memory-like CD4+ and CD8+ T cells in the breakdown of cross-tolerance, resulting in effector cytotoxic T lymphocyte differentiation and the induction of autoimmune disease." (PMID 20856822, 2010). "Furthermore, given the contrasting effects of low dose IL-2 and IFN-γ on pathogenesis of autoimmune diseases, could induction of IL-2 and suppression of IFN-γ production by T cells be achieved simultaneously?" (PMID 40868162, 2025). "Similarly, IL-2−/− and CD25−/− mice develop fulminant autoimmune disease characterized by lymphoproliferation, colitis, and autoantibody production, reinforcing IL-2’s non-redundant role in immune regulation." (PMID 40852720, 2025). "In clinical practice, there have been reports of treatments for autoimmune diseases, human immunodeficiency virus infection, and chemotherapy for metastatic neoplasms with direct administration of IL-2, although no disease has been attributed to IL-2 deficiency or excess." (PMID 38820480, 2024). "The evaluated cytokines can be classified into three broad groups: the proinflammatory Th-1 cytokines: IL-2, IFN-γ, and TNF-α; the counterbalancing Th-2 cytokines: IL-4, IL-5, IL-10, and IL-13; and the Th-17 cytokine IL-17A, which is actively involved in several autoimmune diseases including MS." (PMID 38932415, 2024). "Interleukin 2 (IL-2) is key in the activation of CD4 T-cells and regulates their homeostasis; it is also required for the activation in Treg cells therefore may play a role in autoimmune diseases." (PMID 37755547, 2023). "A second class of IL2-based therapeutics biases the cytokine towards IL2Rα binding; NKTR-358 uses permanent PEG conjugation to selectively induce Treg proliferation without expanding CD8+ and CD4+ T-cells and is undergoing multiple Phase 1 trials for treatment of autoimmune disorders." (PMID 36839922, 2023). "Although low-dose IL-2 administration transiently increases Treg numbers and has been used with some success to treat autoimmune diseases, systemic administration enhances Tregs nonspecifically and may also activate CD8+ T cells and NK cells." (PMID 36618378, 2022). "The functional and phenotypic improvements observed after membrane-attached IL-2 expression in CAR-Tregs will be important step for enhancing CAR-Treg therapies currently being tested in clinical trials for use after kidney and liver transplantation as well as in autoimmune diseases." (PMID 36618378, 2022).
autoimmune disease (continued). "Since the original observation that in the absence of IL-2 signaling mice develop catastrophic autoimmune disease, our knowledge of the complex intersection of multiple underlining conditions contributing to autoimmunity has grown to include multiple T cell populations in addition to Treg cells." (PMID 33986755, 2021). "However, whether IL-2-induced STAT5 activation limits human Th17 differentiation and plays a role in human autoimmune disease remains unclear." (PMID 30150979, 2018). "Numerous clinical studies are investigating the therapeutic potential of IL-2 in autoimmune diseases and focus on the expansion of Tregs; however, it is not known whether the therapeutic efficacy of IL-2 is solely attributable to the expansion of Tregs." (PMID 30150979, 2018). "Our results, showing that IL-2 immune complex can promote the breakdown of peripheral tolerance by memory-like CD8+ T cells in the absence of CD4+ T cells help, have important implications for the development of therapies for autoimmune diseases as well as cancer immunotherapies." (PMID 20856822, 2010). "In the absence of the IL-2 signal, Treg cell numbers are reduced (but not completely absent), they express reduced levels of Foxp3 and other phenotypic and activation markers, and they lose their suppressor function, which result in a fatal lymphoproliferative and autoimmune disease." (PMID 32582190, 2020). "However, it is still not clear whether the promise of LD IL-2 for treatment of autoimmune diseases will be met." (PMID 26793191, 2015). "Therefore, up-to-date clinical data allow us to conclude that so-called “low-dose” IL-2 appropriately administered in the treatment of autoimmune diseases should not surpass 3 × 106 IU/day, and the cumulative dose should not exceed more than 50–100 × 106 IU for a course of therapy." (PMID 25322151, 2014). "Indeed, mice deficient in IL-2, IL-2R, JAK-3, or STAT5A/B have an absent or reduced number of thymic and peripheral CD4+ CD25+ nTreg and consequently develop multiple organ autoimmune diseases." (PMID 21647403, 2011). "Treatment with neutralizing antibodies against IL2, transgenic mice lacking IL2, IL2R or STAT5 show a deficit in Treg cells and develop autoimmune disease." (PMID 39076972, 2024). "While low-dose IL-2 has been used to expand the endogenous pool of Tregs and successfully control chronic graft-versus-host disease (GVHD) and selected autoimmune diseases, similar efficacy has not been observed in organ transplantation." (PMID 38426492, 2024). "Analysis of IL-2, IFN-γ and TNF-α showed that the proportion of MAIT cells producing these cytokines was reduced in women with long-term type 1 diabetes compared with healthy donors regardless of autoimmune disease status." (PMID 34350463, 2021).
Autoimmunity (280 papers, 2004 to 2026). The occurrence of an immune reaction against the organism's own cells or tissues. "The role of the interleukin encoded by the neighboring gene IL2 in autoimmunity seems to be the opposite of that of IL-21." (PMID 39746095, 2025). "IL-2 has been proposed to be a potential master regulator for autoimmunity associated with skin and lung inflammation." (PMID 39846845, 2025). "Therapies with mRNA coding for IL-2 (eventually mutated or fused to albumin) are promising in the context of cancer and autoimmunity." (PMID 39120273, 2024). "With the exception of IL2, these genes have known associations with T cell-mediated autoimmunity and Mendelian IEIs." (PMID 39241920, 2024). "IL-2 has been implicated in a variety of physiological and pathological processes, including immune responses, autoimmunity, transplantation, cancer, and infectious diseases." (PMID 38397895, 2024). "Imbalances between regulatory and effector T cells is thought to contribute to autoimmunity and T1D development, and individuals are often reported with a deficiency in interleukin 2 (IL-2) production." (PMID 36359899, 2022). "Subsequent research showed that IL-2 is necessary for maintaining Treg cells, and its absence results in an intense Treg cell deficiency and autoimmunity because IL-2 encourages Treg cell generation, survival, and activity." (PMID 36187827, 2022). "T reg populations are essential for gestational success, and a correct IL-2—STAT5 signaling with adequate levels of T reg has been associated with the prevention of autoimmunity and human recurrent abortions." (PMID 36012236, 2022). "IL-2 is associated with control of T-cell function and autoimmunity, and over-activity of IL-2 is thought to contribute to the development of classical autoimmune conditions." (PMID 34280516, 2021). "Although IL-2 was originally described as a T cell stimulatory factor, mice deficient in IL-2 or the IL-2 receptor were found to develop severe autoimmunity." (PMID 34003116, 2021). "When disrupted, IL-2-dependent balance of Treg and T effector cells causes autoimmunity and chronic inflammation." (PMID 34685775, 2021). "For example, elegant work has shown that a lack of STAT3 activation prevents the accumulation of Th17 cells in IL-2-deficient mice, resulting in prolonged lifespan and reduced autoimmunity associated with IL-2 deficiency." (PMID 33986755, 2021). "Upon entering the splenic T-cell zone within the white pulp region, activated T cells have been shown to support increased expression of IL-2, which has been linked to the development of autoimmunity." (PMID 32497151, 2020). "The importance of IL-2 in maintaining Treg was further confirmed by their absence in IL-2 deficiency and by the fact that adoptively transferred Treg suppresses the development of autoimmunity in CD122-deficient mice." (PMID 32917054, 2020). "In IL-2-, IL-2Rα-, and IL-2Rβ-deficient models, mice succumb to lethal autoimmunity within 8–12 weeks due to impaired thymic development of Tregs." (PMID 30842774, 2019). "IL-2 is essential for the maintenance of Tregs since, in its absence, a profound deficiency of Tregs occurs leading to autoimmunity." (PMID 31824482, 2019). "Accordingly, major IL-2 dysfunctions in both humans and mice are associated with the development of autoimmunity as well as immunodeficiencies." (PMID 29682583, 2018). "This coincides with the previous findings of dysregulated T cell trafficking to the brains of IL-2-deficient mice attributes to CNS autoimmunity." (PMID 28280495, 2017). "The potential benefit in using IL-2 in immunotherapy for cancer and autoimmunity has been linked to the modulation of immune responses, which partly relies on a direct effect on Tregs populations." (PMID 28708863, 2017).
Autoimmunity (continued). "Interleukin-2 (IL-2) has been used in immunotherapy for cancer and autoimmunity and its beneficial effect has been linked to the modulation of immune responses, which partly relies on a direct effect on Tregs populations." (PMID 28708863, 2017). "IL-2 promotes Tregs and knockout of IL-2 or IL-2-receptor causes lethal autoimmunity, therefore CD28 drives a more regulatory environment while CD40 promotes an inflammatory environment." (PMID 28192476, 2017). "PPARγ has specifically been shown to be a negative regulator of T cell activation, regulating interleukin-2 (IL-2) production in activated T cells, and the loss of PPARγ in T cells contributes to autoimmunity." (PMID 27929420, 2016). "A previous study showed that the aberrant production of IL-2 can disrupt primary human T lymphocytes function by leading to the loss of T cell anergy and induction of autoimmunity." (PMID 27478614, 2016). "Immune tolerance is maintained in part by IL-2 and deficiencies in the IL-2 pathway cause reduced Treg function and an increased risk of autoimmunity." (PMID 25457307, 2015). "Of note, the pathogenic Th17 cells expanding in the reduced IL-2 milieu appeared to be selectively resistant to Treg-mediated inhibition, thus strengthening chronic inflammation in autoimmunity." (PMID 25322151, 2014). "For the most part, loss of IL-2 signaling in these hosts has been attributed to loss of Treg cell development, maintenance and suppressive function leading to lethal autoimmunity." (PMID 24416451, 2014). "This is demonstrated most dramatically in knock-out mice in which a deficiency of Il2, Il2ra, or Il2rb leads to early death due to severe autoimmunity." (PMID 24376757, 2013). "In humans, the presence of an autoimmunity-associated IL2RA haplotype correlates with reduced interleukin-2 responsiveness in stimulated CD4+ T cells and decreased ability of Tregs to suppress the proliferation of autologous effector T cells." (PMID 24154763, 2013). "In recent years, strong genetic and molecular evidence has shown that the IL-2/IL-2R pathway promotes Treg cells development and functional fitness, and functional variations of this pathway can promote susceptibility to autoimmunity." (PMID 21059266, 2010). "Genetic evidence linking the IL-2/IL-2RA pathway to the predisposition of human autoimmunity, and in particular T1 D, has also emerged in recent years." (PMID 21059266, 2010). "The cross-regulation model is consistent with observations in IL-2 deficient mice, which spontaneously develop autoimmunity." (PMID 18509463, 2008). "The importance of IL-2 in lymphocyte homeostasis is shown by a severe autoimmunity in mice deficient in IL-2 signaling components." (PMID 18304352, 2008). "IL-2 supports various lymphocyte subtypes, but its loss results in lethal autoimmunity." (PMID 39403378, 2024). "Therefore, we inferred that the significant increase in serum immunoglobulin and IL-2 in AT was partly due to the activation of autoimmunity caused by diarrhea." (PMID 36829999, 2023). "Nevertheless, due to its pleiotropy, IL-2, even applied in low doses, may activate also potentially harmful cells, which bears the risk to induce or worsen autoimmunity." (PMID 33868284, 2021). "IL‐2 was originally discovered in the 1970s as a T cell growth factor, with subsequent work showing that mice lacking genes encoding for IL‐2, IL‐2Rα, or IL‐2Rβ had a paucity of Tregs and developed lethal autoimmunity." (PMID 34375446, 2021). "In addition, CD21low B cells produce significantly higher amounts of IgM as compared to näive B cells upon stimulation with CD40L, IL-2 and IL-10, and higher IgM levels have been associated with the development of autoimmunity in CVID patients." (PMID 34290696, 2021). "IL-2 deficiency may contribute to autoimmunity in SLE patients and lupus-prone mice by inducing paucity of Tregs, defective activation-induced cell death (AICD) and increased IL-17 production." (PMID 35069220, 2021).
Autoimmunity (continued). "Given that FOXP3 is the master regulator of Treg differentiation, the reduced expression of this transcription factor in response to IL-2 in cells carrying the SNP might increase the risk of autoimmunity by hampering Treg functions." (PMID 31297117, 2019). "A reduction of IL-2 could potentially reduce Treg cell numbers and put the astronauts at a greater risk for autoimmunity or overt inflammatory conditions." (PMID 31554863, 2019). "Loss of brain-derived IL-2 results in neurobiological and behavioral abnormalities, and may contribute to the development of CNS autoimmunity by modifying the neuroimmunological milieu of the brain." (PMID 25961067, 2015). "In the present study, we sought to determine whether cognitive alterations in IL-2KO mice are due to the loss the IL-2 gene in the brain and/or autoimmunity resulting from loss of the gene in the peripheral immune system." (PMID 25961067, 2015). "Together, these data suggest that multiple mechanisms converge in disease leading to decreased response to IL-2, a phenotype that may eventually lead to loss of tolerance and autoimmunity." (PMID 24376757, 2013). "In fact, mice deficient in IL-2, IL-2Rα, and IL-2Rβ exhibit autoimmunity." (PMID 23676143, 2013). "Conversely, CD4+CD25+ nTreg from wild-type mice transferred to IL-2-deficient mice fail to prevent autoimmunity and in vitro suppression activity is completely abrogated by selective blocking of the IL-2 receptor on nTreg during a coculture with responder T cells." (PMID 21647403, 2011). "Similarly, JAK3−/− mice have low frequency of nTregs, increased amount of autoreactive T cells, and develop autoimmunity as is the case for IL-2-deficient and IL-2R-deficient mice." (PMID 21647403, 2011). "However, given the already elevated cytotoxic potential and pro-inflammatory profile in elderly females, systemic IL-2 or IL-15 administration could carry risks, such as immune overstimulation or increased susceptibility to autoimmunity." (PMID 41194200, 2025). "Notably, both IL-2 and IL-2R-deficient mice develop life-threatening autoimmunity." (PMID 35326431, 2022). "Decreased IL-2 by HE may be associated with the balance between inflammation and autoimmunity." (PMID 31308153, 2019). "Experiment 3 therefore sought to determine if IL-2KO mice have deficits in fear-related learning in a contextual fear discrimination paradigm, and if fear-conditioning abnormalities were associated with peripheral autoimmunity and whether one or both IL-2 gene alleles are deleted." (PMID 25961067, 2015). "Thus, defects within the IL-2/CD25 signaling axis may constitute a conserved immune/AICD defect predisposing to autoimmunity." (PMID 19956753, 2009). "However, all three of IL-2, IL-15 and IL-21 have been implicated in autoimmunity, and using such cytokines to activate endogenous NK cells may favour inflammation and promote autoreactivity." (PMID 18053164, 2007). "The instability of tissue Tregs, their conversion into proinflammatory ex-Tregs, and the loss of key homeostatic signals (e.g., IL-2, IL-33, and AREG) are common threads across autoimmune pathologies." (PMID 40933988, 2025). "Administration of IL-2 has been demonstrated as an effective strategy to induce in vivo Treg expansion and prevent autoimmunity in numerous mouse models, such as in NOD mice." (PMID 41567805, 2025). "High doses of IL-2 promote autoimmunity by activating effector T cells, whereas low doses of IL-2 induce only the development of Treg cells but not effector T cells." (PMID 40181974, 2025). "Methotrexate, Azathioprine, and Mycophenolate Mofetil are well-established in autoimmunity and offer predictable suppression of IL-2 and CD4 + T cells." (PMID 41057909, 2025). "Consistent with systemic IL-2 therapy, β-cell-specific IL-2 delivery persistently suppressed β-cell autoimmunity and provided long-term protection against diabetes onset in both preclinical and advanced disease stages." (PMID 41567805, 2025).